BRCA1 (BRCA1 DNA repair associated)
Diseases named in the same sentence as BRCA1 in open-access papers (continued):
Sharing a sentence is not in itself a finding about the gene and the disease.
breast cancer (continued). "In practice, this suggests that women with ER+ HER2 positive breast cancers should be advised that they are unlikely to harbour a BRCA1/2 mutation unless there are other very suggestive features in their own personal or family histories (other more typical breast cancer or ovarian cancer)." (PMID 27796713, 2017). "This phenomenon prompts that the genesis of breast cancer may be promoted by splicing BRCA1." (PMID 28881705, 2017). "This is reflected by guidelines on breast cancer risk management in BRCA1/BRCA2 carriers, which do not give clear recommendations for women with a previous diagnosis of ovarian cancer, but support discussion of the option of risk-reducing breast surgery with women on a case-by-case basis." (PMID 28780755, 2017). "However, this research would benefit greatly from larger population-based studies that might encourage health care workers to incorporate BRCA1 staining in breast cancer prognosis algorithm." (PMID 28863181, 2017). "Thus, the role of BRCA1 and BRCA2 mutations in the pathogenesis of breast cancer led us to hypothesize that patients with these mutations might have a worse prognosis than non-carriers." (PMID 29152070, 2017). "A number of heterozygous mutations in FA-related genes are implicated in the susceptibility to several cancers: BRCA1 and BRCA2 mutations are associated with breast and ovarian cancer and similarly Fanconi anemia complementation group protein J (FANCJ) mutations predispose to breast cancer." (PMID 28471392, 2017). "There is also promising data that determinants for breast cancer might perform in a different way for carriers of BRCA1 or BRCA2 variants than for females lacking hereditary vulnerability because of these genes." (PMID 28969709, 2017). "A complete loss or significantly reduced BRCA1 protein expression is often found in sporadic breast cancer cases despite the absence of genetic or epigenetic aberrations, suggesting the existence of other regulatory mechanisms controlling BRCA1 protein expression." (PMID 29156836, 2017). "Besides, 73.9% of the families in the BRCA1-pathogenic group had 3 or more cases of breast cancer in their families, while 63.6% and 64.3% of the families with VUS at BRCA1 gene and BRCA1-WT respectively, reported up to two cases of breast cancer in the family (p = 0.007)." (PMID 27926510, 2017). "Thus, HSF1-mediated DDR is a major mechanism of the addiction of BRCA1-null mammary tumors to HSF1, and could be a target for the treatment of a specific type of malignant tumors." (PMID 29158484, 2017). "An important role for BRCA1 expression and subcellular localization in breast cancer progression is indicated by its loss and altered distribution in a large proportion of non-familial breast cancers." (PMID 28863181, 2017). "This may be important, as BRCA1/2-mutation carriers are potentially at increased CVD risk because of early menopause around age 40 (due to risk-reducing salpingo-oophorectomy), or cardiotoxic effects after adjuvant breast cancer treatment." (PMID 27966054, 2017). "However, some subtypes of alternative BRCA1 splicing are correlated to breast cancer." (PMID 28881705, 2017). "Thus, we investigated the prevalence of BRCA1/2 large genomic rearrangements using multiplex ligation-dependent probe amplification in high-risk breast cancer patients with negative results for BRCA1/2 mutation by direct sequencing." (PMID 28205045, 2017). "However, information on influential covariates such as treatment, family history of breast cancer, and BRCA1/2 mutation carrier status was not available." (PMID 28724391, 2017).
breast cancer (continued). "Unlike other familial breast cancers such as those with BRCA1 mutation, breast cancers with CS are generally hormone receptor-positive and may have a favorable clinical course." (PMID 28741261, 2017). "Also, researchers analysing the impact of (adjuvant) radiotherapy on breast cancer risk in BRCA1 and BRCA2 mutation carriers reported no univocal conclusion." (PMID 27184744, 2016). "The impact of mutations in either gene can be dramatic; 65 % and 45 % of women with deleterious mutations in BRCA1 or BRCA2, respectively, will develop breast cancer by age 70, and the risk increases to 85 % and 84 %, respectively, for women with a family history of breast cancer." (PMID 27716388, 2016). "Therefore, regardless of family history, all men with breast cancer should be routinely screened for BRCA1 and BRCA2 mutations." (PMID 27377827, 2016). "BRCA1/2 mutation carriers and non-carriers were diagnosed with breast cancer at similar age." (PMID 27553291, 2016). "Indeed, aberrant methylation at BRCA1 is evident in only eleven tumor DNA samples (and the corresponding blood derived DNA samples) despite the highly selected nature of the samples (early onset breast cancer)." (PMID 27902704, 2016). "Therefore, the prevalence of BRCA1/2 mutation in unselected Chinese breast cancer patients has not been fully explored." (PMID 27257965, 2016). "In addition, a number of population studies have revealed that a large proportion of breast cancer patients with a BRCA1 or BRCA2 germline mutation have no history of the disease in the family." (PMID 27129401, 2016). "Women at high risk for breast cancer and OVCA, having a mutation in either BRCA1 or BRCA2 genes, may prophylactically take selective estrogen receptor modulators (SERMs), such as 4-hydroxytamoxifen (4OHT), to decrease their risk of developing breast cancer." (PMID 26879975, 2016). "Besides BRCA1 (and BRCA2) mutation carriers, also other women with increased risk of breast cancer could benefit from such a prevention strategy." (PMID 27881737, 2016). "However, prevalence of BRCA1 and BRCA2 mutations is low in sporadic breast cancer patients." (PMID 27283966, 2016). "Indeed, at least 60–70 % of all breast cancers caused by an inherited BRCA1 germline mutation are diagnosed as TNBC, while inactivation of the second major breast cancer susceptibility gene BRCA2 is more frequently observed in hormone receptor-positive breast cancers." (PMID 27756336, 2016). "Crossover designs would ultimately only provide evidence on the sequence of applying carboplatin-olaparib or capecitabine in BRCA1- or BRCA2-mutated breast cancers but not on whether the regimen targeting the BRCA defect is better than a control treatment." (PMID 27323902, 2016). "Also, this study includes selected breast cancer patients with a high probability of carrying a pathogenic BRCA1/2 germline mutation so it is not reasonable to generalize these results to the entire population." (PMID 27129401, 2016). "Lamin A/C loss correlates with decreases in BRCA1, and to a lesser extent in 53BP1 levels, key factors in DNA repair by homologous recombination (HR) and non-homologous end joining (NHEJ) respectively, as previously observed in mouse fibroblasts and breast cancer cells." (PMID 27145372, 2016). "Thus, future studies aimed at targeted delivery of PB into BRCA1-defective breast cancers could open up new avenues for the complete abrogation of the cancer, including CSCs, aiding relapse-free survival after chemotherapy." (PMID 27229859, 2016). "The aim of this study was to determine the impact of CPM on 20-year overall and disease-free survival and quality-adjusted life expectancy for women without a BRCA1/2 mutation, taking into consideration age at diagnosis, disease stage, ER status, and degree of family history of breast cancer." (PMID 27650678, 2016).
breast cancer (continued). "However, none of the SNPs showed associations with breast cancer risk, including rs11099601, which had a P-value of 0.89 and 0.78 in BRCA1 and BRCA2 carriers respectively." (PMID 27792995, 2016). "However, it has been reported that BRCA1-associated breast cancers are not homogeneous in respect of their response to neoadjuvant chemotherapy, and in the present report, we point to DNA damage repair as the molecular background of this heterogeneity." (PMID 27626685, 2016). "So far, no report exists on immunhistochemical TR reactivity in BRCA1 associated breast cancer." (PMID 26029931, 2015). "In this study, we performed germline mutation analysis of the entire coding region of PALB2 in a cohort of 1996 breast cancer index cases referred to familial cancer clinics for genetic testing and tested negative for BRCA1 and BRCA2 mutations as well as 1998 Australian cancer-free female controls." (PMID 26283626, 2015). "However, to the best of our knowledge no data exist upon thyroid function in BRCA1 associated breast cancers so far." (PMID 26029931, 2015). "In conclusion, our study provides evidence that the b allele of the BsmI in the VDR gene may be associated with an increased breast cancer risk in Pakistani women who are negative for BRCA1/2 germline mutations." (PMID 26517870, 2015). "The aim of this study was to evaluate the prevalence of this variant and determine its contribution to the development of breast cancer in sporadic cases and also in members of breast cancer families who tested negative or positive for a deleterious mutation in BRCA1/BRCA2." (PMID 25674498, 2015). "With regard to breast cancer, elevated Sp1 was found to regulate thousands of genes that are critically involved in mammary tumorigenesis and metastatic progression, such as vascular endothelial growth factor, urokinase plasminogen activator and its receptor, cyclin D1 and BRCA1." (PMID 25918249, 2015). "However, this standard incidence ratio was reported to be indicative of some association of early-onset breast cancer and pancreatic cancer through causes unrelated to BRCA1 mutations, although no other proposed causes were suggested." (PMID 26236408, 2015). "Furthermore, Analysis of a public database identified significantly reduced PIG3 mRNA levels in 392 breast cancer cell samples with a BRCA1 mutation, compared with 206 breast cancer cell samples without BRCA1 mutation." (PMID 25797244, 2015). "Therefore, females with a mutated BRCA1/2 gene are five times more likely to develop breast cancer than someone without a mutation." (PMID 26236408, 2015). "Therefore we hypothesized that basal-like breast cancer cells with overexpression of LSD1 may be sensitive to PARP inhibitor via suppression of BRCA1." (PMID 25679396, 2015). "Interestingly, in the present study, treatment with ROSI caused induction of BRCA1 expression in PPARγ-WT, but not PPARγ-MG KO mouse mammary tumours." (PMID 25889730, 2015). "Thus, given the rare frequency of somatic BRCA1 mutations (despite the high prevalence of BRCA1 heterozygous loss), a role for BRCA1 deficiency in sporadic breast cancer is not established." (PMID 25825707, 2015). "Accordingly, a decrease in BRCA1 expression leads to a decreased proficiency in DNA repair, increased cisplatin sensitivity and improved survival in non-small cell lung cancer, breast cancer, advanced esophageal squamous cell carcinoma and ovarian cancer patients." (PMID 25912308, 2015). "Therefore, this study aimed to investigate the presence of TRs in breast cancers diagnosed in patients carrying a BRCA1 germline mutation as compared to sporadic (i.e. without any family or personal history of breast cancer) cases." (PMID 26029931, 2015).
breast cancer (continued). "This current Singapore study, based on 359 Asian breast cancer patients prospectively accrued from a risk-assessment clinic, has identified ER-negativity, TNBC status and a FH of HBOC as predictive factors to increase the likelihood of detecting BRCA1 and BRCA2 mutations." (PMID 26221963, 2015). "However, the contribution of the BRCA1 or BRCA2 mutation in breast cancer incidence has not yet been investigated in Argentina." (PMID 25624909, 2015). "Although heterozygous germ-line mutations in the BRCA1/2 genes render a risk of up to 85% for the development of breast cancer, and 10–40% for ovarian cancer, only a small fraction of tumors are BRCA-deficient, accounting for 3–5% of all breast cancers and 15% of ovarian cancers." (PMID 25621047, 2015). "Thus, gene mutations and alternative splicing in the BRCA1 gene might have effects on the nuclear import and distribution of the BRCA1 protein, which might play a role in breast cancer development." (PMID 25908947, 2015). "They confirmed that the risk of CBC in noncarriers of BRCA1/2 mutation with a family history was highest in women diagnosed at an earlier age with their index breast cancer (<45 years), those with a young first-degree relative, particularly with bilateral disease." (PMID 25692038, 2015). "The BsmI polymorphism in the VDR gene may be associated with an increased breast cancer risk in Pakistani women negative for BRCA1/2 germline mutations." (PMID 26517870, 2015). "Finally, partial sporadic breast cancer with BRCA1 hypermethylation may exhibit favorable clinicopathological status." (PMID 25789047, 2015). "However, as in our study, MALDI-TOF and methylation-specific multiplex ligation assays by two other groups, each using flash-frozen breast cancers and matching control tissue, revealed only low percentages of cancers with greater BRCA1 methylation compared with controls." (PMID 26510686, 2015). "The majority of these mutations identified in familial breast cancer result in the partial or complete deletion of exons or intronic sequence inserts, which may ultimately yield non-functional, truncated BRCA1 and BRCA2 proteins." (PMID 25624909, 2015). "Such knowledge may be particularly important for high risk women who are determined not to carry a BRCA1/2 mutation, as their risk of developing contralateral breast cancer may be substantially lower than initially suspected." (PMID 25700605, 2015). "Furthermore, BRCA1/2-related breast cancers also presented a higher percentage of VEGFA, HIF1A, FAK and ANGPT2 gene overexpression compared to the BRCAX breast tumour group (VEGFA: 62% vs 9%, p=0.04; HIF1A: 62% vs 0%, p=0.004; FAK: 62% vs 18%, p=0.073; ANGPT2: 50% vs 45%, p= 1.00)." (PMID 25333258, 2015). "Mutations of BRCA1 account for half of all hereditary breast cancers; and in 30-40% of sporadic cancers, BRCA1 expression is absent or reduced, suggesting a wider role in breast cancer." (PMID 26575173, 2015). "The 2.0% pathogenic mutation rate of the RECQL gene in familial breast cancer patients is remarkable and may be suitable for screening the mutations in BRCA1/2- negative breast cancer patients." (PMID 25945795, 2015). "To determine the germline mutations in the RECQL gene in an additional cohort of familial breast cancer patients, we screened the entire coding region of RECQL gene using Sanger sequencing assays in 439 familial breast cancer patients without BRCA1/2 mutations." (PMID 25945795, 2015).
breast cancer (continued). "A mechanism that may contribute to reducing expression of BRCA-1 in sporadic breast cancers is epigenetic inactivation, which refers to modifications in DNA CpG methylation, histone posttranslational modifications, chromatin remodeling factors, and non-coding RNAs." (PMID 26715507, 2015). "Primary breast cancer treatments may be different for BRCA1 and BRCA2 mutation carriers compared to non-carriers, mostly related to different pathological features of tumours in carriers (part A)." (PMID 25816289, 2015). "In contrast, BRCA1 associated cancers characterized as TRβ positive presented a significantly higher five-year survival rate as compared to TRβ-negative patients (p = 0.007), while TRβ failed to be of prognostic significance in sporadic breast cancer." (PMID 26029931, 2015). "Indeed, 40-50 % of women with a BRCA1 or BRCA2 mutation do not develop breast cancer by 70 years of age." (PMID 26538066, 2015). "Furthermore, variation in TUBG1 was found to be associated with breast cancer risk in a hospital-based case-control study, but has not been assessed in BRCA1/2 mutation carriers." (PMID 25830658, 2015). "Unlike sporadic cases, BRCA1 associated breast cancers display a higher incidence of medullary or basal-like histology and might overexpress cell cycle stimulator genes." (PMID 26029931, 2015). "Further, TR positivity was also associated with five-year survival (TRα positivity—reduced five-year survival; TRβ positivity—advanced five-year survival) in ER negative (TRα: p = 0.032; TRβ: p = 0.020), PR negative (TRα: p = 0.011; TRβ: p = 0.029) BRCA1 mutated breast cancer." (PMID 26029931, 2015). "All these data reinforced our first hypothesis, suggesting a sporadic HER2-positive breast cancer with no hallmarks of BRCA1-driven tumor in a woman with BRCA1 germline mutation." (PMID 26426992, 2015). "To interrogate the effects of BECN1 and BRCA1 in breast cancer, we studied their mRNA expression patterns in breast cancer patients from two large datasets: The Cancer Genome Atlas (TCGA) (n = 1067) and the Molecular Taxonomy of Breast Cancer International Consortium (METABRIC) (n = 1992)." (PMID 25825707, 2015). "Theoretically, PARPi activity could be expanded to breast cancers without BRCA1/2 mutations; several preclinical experiments support this possibility by focusing on the impairment of the HR pathway." (PMID 26268938, 2015). "Here, by sequencing the entire exomes of nine early-onset familial breast cancer patients without BRCA1/2 mutations (diagnosed with breast cancer at or before the age of 35) we found that two index cases carried a potentially deleterious mutation in the RECQL gene (RecQ helicase-like; chr12p12)." (PMID 25945795, 2015). "This study screened Australian individuals with breast cancer who had been referred to a Familial Cancer Centre for genetic testing and in whom no pathogenic BRCA1 and BRCA2 variant could be identified." (PMID 26283626, 2015). "Genetic factors play an important role in breast cancer (BC) development, including the presence of BRCA1, BRCA2, ATM, and other genes, but only 5% of BC incidence can be explained by mutation in these high-penetrance genes." (PMID 25636233, 2015). "In the current study, the hypothesis is that the absence of BRCA1 transcript is associated with promoter methylation in sporadic types of breast cancer." (PMID 25789047, 2015). "In this sense, we found that the group of early-onset breast cancer patients (≤35 yo) is at a higher risk of carrying pathogenic mutations in the BRCA1/2 genes with a positive detection rate of 35%, which reached 42% in cases with a family history of breast cancer (not shown)." (PMID 24884479, 2014).